BRCA1 (BRCA1 DNA repair associated)
Diseases named in the same sentence as BRCA1 in open-access papers (continued):
Sharing a sentence is not in itself a finding about the gene and the disease.
ovarian carcinoma (continued). "Skewed activation in women with breast and ovarian cancers, at least in part, has been attributed to BRCA1 and to a lesser extend BRCA2 mutations." (PMID 25036526, 2014). "In summary, this is the most comprehensive BRCA1/2 mutation screening study of Brazilian BC patients from families with hereditary breast and ovarian cancer." (PMID 24884479, 2014). "The BRCA genes do not demonstrate equal penetrance and the lifetime risk of developing epithelial ovarian cancer for women with a BRCA1 or BRCA2 mutation is up to 66% and 27%, respectively." (PMID 27382614, 2014). "The score of ovarian cancer patients with BRCA1/2 mutation was significantly higher than wild-type patients (p = .02, Wilcoxon rank sum test)." (PMID 25437005, 2014). "These were identified through genome-wide association studies (GWAS) of breast or ovarian cancer in the general population or through BRCA1- and BRCA2-specific GWAS." (PMID 24698998, 2014). "Although BRCA1 gene mutations are rare in sporadic breast and/or ovarian cancers, BRCA1 protein expression is often reduced in the sporadic cancer specimens." (PMID 25426449, 2014). "Nearly 30% of HBOC patients harbor germ line point mutations or genomic structural rearrangements that result in copy number variations (CNVs) in BRCA1/2 genes, with a lifetime risk of 45-70% for BC and 20-40% for ovarian cancer." (PMID 24884479, 2014). "Breast and ovarian cancer mostly arise sporadically, but a small number of cases (approximately 10%) of these cancers are associated with mutations in BRCA1/2 genes." (PMID 25429284, 2014). "BRCA1 is a multifunctional protein best known for its role in DNA repair and association with breast and ovarian cancers." (PMID 25522274, 2014). "Compromised homologous recombination (HR) due to loss of BRCA1/2 is a dominant molecular feature of HGS ovarian cancer and other epithelial malignancies." (PMID 25060187, 2014). "For example, antioxidant phytochemicals such as sulforaphane or resveratrol can be helpful to prevent breast or ovarian cancers that carrying BRCA1 mutations by removing ROS." (PMID 24704793, 2014). "We found four SNPs associated with ovarian cancer risk with a p-trend<0.01 in BRCA1 or BRCA2 mutation carriers." (PMID 24698998, 2014). "In this context, it is interesting to note that a variety of genome-wide association studies of BRCA1/2 mutation carriers recently identified some genetic loci, which affect BRCA1/2-associated cancer risks for breast and ovarian cancers." (PMID 25036526, 2014). "We found that 16 % of unselected cases of ovarian cancer in Belarus carried one of three founder mutations in the BRCA1 gene." (PMID 24770866, 2014). "Here, we show that the hypomethylated ETS1 motif is a key regulatory element for the PARP1 gene in BRCA1-mutated ovarian cancer." (PMID 24448423, 2014). "Among the 25 women with ovarian cancer and a BRCA1 mutation, only eight reported a first- or second-degree relative with breast or ovarian cancer (32 %)." (PMID 24770866, 2014). "Poly(ADP-ribose) polymerase inhibitors (PARPi) have shown clinical activity in patients with germline BRCA1/2 mutation (gBRCAm)-associated breast and ovarian cancers." (PMID 24616882, 2014). "BRCA1 germline mutation variants result in various changes in the structure of the BRCA1 proteins that impact breast or/and ovarian cancer risk and clinical outcomes." (PMID 24348864, 2014). "Interference with BRCA1 expression and/or functions leads to high risk of breast or/and ovarian cancer." (PMID 24586743, 2014).
ovarian carcinoma (continued). "We found that, not only BRCA2 mutation carriers, but also BRCA1 mutation carriers had significantly improved survival than wild-type ovarian cancer patients." (PMID 25437005, 2014). "CIMBA studies have so far demonstrated that more than 25 SNPs are associated with the risk of developing breast or ovarian cancer for BRCA1 or BRCA2 carriers." (PMID 24698998, 2014). "The breast cancer susceptibility gene 1 (BRCA1) is a significant breast and ovarian cancer susceptibility gene; it has been mapped to chromosome 17q21 and encodes a nuclear protein, which is comprised of 1863 amino acids." (PMID 24944674, 2014). "Germline mutations in the breast cancer susceptibility gene 1 (BRCA1) extensively increase the risk of breast and ovarian cancers." (PMID 25426449, 2014). "Several studies have shown a significant heterogeneity of breast and/or ovarian cancer prevalence among various mutations of BRCA1 gene." (PMID 24348864, 2014). "OC patients with a family history of breast or ovarian cancer present high probability of carrying a mutation in BRCA1 or BRCA2." (PMID 25136623, 2014). "Both BRCA1/BRCA1a K109R and disease associated C61G mutants, which are localized mainly in the cytoplasm, fail to inhibit the growth of breast and ovarian cancer cells." (PMID 25594072, 2014). "Carriers of BRCA mutations are at increased risk of both breast and ovarian cancer; such risks are consistently estimated to be higher in BRCA1 than in BRCA2 mutation carriers; moreover, the risk is higher for breast than for OC." (PMID 25136623, 2014). "In more than 70% of families with a strong history of breast and ovarian cancers, pathogenic mutation in BRCA1 or BRCA2 cannot be identified, even though hereditary factors are expected to be involved." (PMID 24479546, 2014). "In agreement with other reports on BRCA1 associated ovarian carcinomas, invasive epithelial cancer of serous histology was found to be the most common histological subtype among BRCA1 c.190T>C mutation carriers." (PMID 24516540, 2014). "Investigating the functional significance of loss of BRCA1 in women with ovarian cancer is critical to understanding how BRCA1 dysfunction results in ovarian cancer." (PMID 25594072, 2014). "Examples of this occurrence in ovarian cancer include the human MutL homolog 1 (hMLH1) and breast cancer susceptibility gene 1 (BRCA1), which are two critical genes that transcribe proteins involved in the DNA damage response and DNA mismatch repair." (PMID 24782983, 2014). "The aim of this study was to estimate the frequency of the three BRCA1 founder mutations in unselected series of ovarian cancer patients from Belarus." (PMID 24770866, 2014). "Currently, platinum-based therapy is a major option for BRCA1/2-mutated tumors, such as ovarian cancer." (PMID 25158060, 2014). "PARP inhibitors that block single-strand break repair (SSBR), a pathway related to BER, have shown clinical benefit in BRCA1/2 germ line-deficient breast and ovarian cancers." (PMID 25111287, 2014). "Although there was no significant change in the expression of PCAF, the expression levels of GCN5 and ETS1 factors were increased in BRCA1-mutated ovarian cancer." (PMID 24448423, 2014). "Ovarian cancer (OC) mostly arises sporadically, but a fraction of cases are associated with mutations in BRCA1 and BRCA2 genes." (PMID 25136623, 2014).
ovarian carcinoma (continued). "Hennessy and colleagues performed BRCA1/2 sequencing on 235 unselected ovarian cancers and found that 19% of the sample had detectable mutations in BRCA1 (N = 31) or BRCA2 (N = 13)." (PMID 24579064, 2014). "This study for the first time investigated the alleged BRCA1/2 interaction with low FMR1 mutations in an ovarian cancer model." (PMID 25036526, 2014). "Germline mutations in BRCA1 or BRCA2 are present in approximately 18% of hereditary ovarian cancers." (PMID 25051360, 2014). "It is now appreciated in the ovarian cancer literature that upon treatment with standard platinum-based chemotherapy, BRCA1- and BRCA2-associated malignancies have an improved prognosis compared to sporadic epithelial ovarian cancers." (PMID 25177489, 2014). "The aim of the present study was to determine the aberrant promoter methylation of BRCA1 in benign and malignant ovarian tumor tissues, to establish the association with the clinicopathological significance and the prognostic value." (PMID 24944674, 2014). "It is currently estimated that about 30%–50% of hereditary breast and ovarian cancers develop in BRCA1 and 2 mutation carriers." (PMID 23644885, 2013). "Identifying a mutation in the BRCA1 gene among breast and/or ovarian cancer families is important, as it enables carriers to take preventive measures." (PMID 23536787, 2013). "On the other hand, BRCA1 or BRCA2 mutations besides the three most common ones have also been reported in Ashkenazi Jewish women with breast/ovarian cancer although at much lower frequencies." (PMID 23638402, 2013). "Lifetime risks of breast and ovarian cancer, are as high as 80% and 40%, respectively, among women carrying BRCA1 mutations, while they are characterized by elevated cancer risk at younger ages." (PMID 23586058, 2013). "Here we use the results from this study, in combination with previously identified modifiers, to obtain absolute risks of developing breast and ovarian cancer for BRCA1 mutation carriers based on the joint distribution of all known genetic risk modifiers." (PMID 23544013, 2013). "This study also showed that the most common phenotype of BRCA1-associated ovarian carcinomas is high-grade serous histology and advanced stage disease." (PMID 23536787, 2013). "Based on the distribution of ovarian cancer risk modifiers, the 5% of BRCA1 mutation carriers at lowest risk will have a lifetime risk of developing ovarian cancer of 28% or lower whereas the 5% at highest risk will have a lifetime risk of 63% or higher." (PMID 23544013, 2013). "No other SNPs from the 4q32.3 region on the iCOGS array were more significantly associated with ovarian cancer for BRCA1 carriers." (PMID 23544013, 2013). "Most ovarian cancers are due to sporadic events and 8–10% are attributable primarily to germline mutations in breast cancer 1 (BRCA1) or BRCA2 genes." (PMID 23964347, 2013). "The minor allele of rs2532348 (MAF = 0.21), which tags H2, was associated with increased ovarian cancer risk for BRCA1 mutation carriers." (PMID 23544013, 2013). "Over the past years BARD1 (BRCA1-associated RING domain 1) has been considered as both a BRCA1 (BReast Cancer susceptibility gene 1, early onset) interactor and tumor suppressor gene mutated in breast and ovarian cancers." (PMID 24349422, 2013). "Other interpretations of these data are possible, but they do suggest differences in the mechanisms for development of breast vs. ovarian cancer in BRCA1-mutation carriers." (PMID 23802008, 2013). "Two (0.6%) PALB2 mutation carriers were reported in a study of 360 ovarian cancer cases that were also screened for BRCA1, BRCA2 and other recently described cancer susceptibility genes." (PMID 23302520, 2013).
ovarian carcinoma (continued). "These included SNPs in the 9p22 and 3q25 loci previously associated with ovarian cancer risk in both the general population and BRCA1 carriers." (PMID 23544013, 2013). "Previous studies are consistent with this observation and recommendation, reporting BRCA1 mutation prevalence in hereditary ovarian cancer patients from 24–66%." (PMID 23536787, 2013). "The presence of Spanish family who suffered from ovarian cancer and early onset ovarian cancer or BC is a major clue for the screening of BRCA1 and BRCA2 gene mutations." (PMID 24312913, 2013). "Associations with breast or ovarian cancer risk for loci previously reported to be associated with cancer risk for BRCA1 mutation carriers." (PMID 23544013, 2013). "Our contribution to this area of investigation was to establish relevance in the BRCA1/2-negative high-risk breast/ovarian cancer Pakistani population by assessing the prevalence of CHEK2 mutations." (PMID 23806170, 2013). "In another study 11.5% of all ovarian cancer cases in Colombia were attributable to a single BRCA1 founder mutation, while 15.6% of the total cohort was positive for mutations in either BRCA1 or BRCA2." (PMID 23536787, 2013). "Molecular screening of consecutive breast and ovarian cancer patients revealed that 3.77% of breast cancer and 9.9% of ovarian cancer patients had been harboring one of the BRCA1 founder mutations." (PMID 23767878, 2013). "Approximately 10 % of ovarian cancer cases are attributed to the inheritance of a BRCA1 or 2 mutation." (PMID 23553196, 2013). "In terms of histological features, ovarian cancer from both BRCA1 and BRCA2 mutation carriers were found to predominantly belong to the high-grade serous carcinoma subtype." (PMID 23344037, 2013). "Breast cancer susceptibility gene 1 (BRCA1) was the first gene assigned responsible for developing hereditary breast and ovarian cancer which manifests as a HBOC syndrome (Hereditary Breast and Ovarian Cancer Syndrome)." (PMID 23941236, 2013). "In the combined analysis of stage 1 and 2 samples (9866 unaffected, 1839 affected), 62 SNPs in 17 regions were associated with ovarian cancer risk for BRCA1 carriers at P<10−4." (PMID 23544013, 2013). "We further confirmed associations with loci previously shown to be associated with breast or ovarian cancer risk for BRCA1 mutation carriers." (PMID 23544013, 2013). "In adults, epithelial ovarian cancers have been associated with dominant negative mutations in gene products (BRCA1/2) that play a critical role in DNA damage repair." (PMID 23641362, 2013). "An additional group of 229 high-risk BRCA1/2-negative breast/ovarian cancer patients (Group 2) were screened for the identified CHEK2 mutations." (PMID 23806170, 2013). "One study, investigating 50 patients versus 40 controls, demonstrated an association between ovarian cancer and gene hypermethylation in at least one of six genes, including BRCA1." (PMID 23344037, 2013). "Breast and ovarian cancer risk estimates for BRCA1 mutation carriers vary by the degree of family history of the disease, suggesting that other genetic factors modify cancer risks for this population." (PMID 23544013, 2013). "BRCA1 germline mutations have been correlated to the increasing risk of developing breast and ovarian cancer." (PMID 23497550, 2013). "A total of 32,557 SNPs on the iCOGS array were selected on the basis of the BRCA1 GWAS for the purpose of identifying breast and ovarian cancer risk modifiers for BRCA1 mutation carriers." (PMID 23544013, 2013). "Ovarian cancers carrying BRCA1 and BRCA2 mutations (mBRCA) display massive chromosomal alterations, and are more sensitive to DNA cross-linking agents containing platinum, and to PARP inhibitors." (PMID 24265793, 2013).
ovarian carcinoma (continued). "In this study we have established the prevalence of BRCA1 mutations in a group of 698 Greek ovarian cancer patients, 106 of which were familial cases and 592 apparently sporadic." (PMID 23536787, 2013). "Ovarian cancers associated with BRCA1 mutation are more often serous adenocarcinomas (90%) compared to women without this mutation (50%)." (PMID 24098868, 2013). "The lifetime risk of ovarian cancer in patients with a BRCA1 mutation is between 40 and 60 % compared with the general population risk of 1.8 %." (PMID 23553196, 2013). "In a Polish study, BRCA1 or BRCA2 germline mutations were found in 13.9% of consecutive ovarian cancer patients, 11% of which was attributable to BRCA1." (PMID 23536787, 2013). "BRCA1 located in chromosome 17q21, and was identified as a breast and ovarian cancer susceptibility gene." (PMID 23497550, 2013). "To systematically search for loci associated with breast or ovarian cancer risk for BRCA1 carriers we previously conducted a two-stage genome-wide association study (GWAS)." (PMID 23544013, 2013). "Of the top hits for these phenotypes, SNP rs199533 in NSF, previously associated with Parkinson's disease and rs9915547 associated with intracranial volume were strongly associated with ovarian cancer (P<10−9 in BRCA1/2 combined)." (PMID 23544013, 2013). "Sixty-five percents of Thai familial and early-onset breast/ovarian cancer exhibited BRCA1/2 mutations within coding region." (PMID 23393598, 2013). "Recent studies on BRCA1/BRCA2 have concluded that a germline mutation in BRCA1 or BRCA2 was associated with improved survival in ovarian cancer patients and BRCA2 carriers had the best prognosis (40–, 42)." (PMID 23964347, 2013). "Identifying individuals with mutations in breast/ovarian cancer susceptibility genes is clinically important as BRCA1/2 carriers have been shown to have increased sensitivity to the novel poly-ADP-ribose (PARP) inhibitors." (PMID 23536787, 2013). "It is interesting to note that BRCA1-mutated ovarian cancer showed dramatically increased expression of EGFR compared with the remaining three groups." (PMID 24321281, 2013). "A number of similar studies in other populations have been published, giving prevalence for BRCA1 mutations in ovarian cancer patients from 8 to 11%." (PMID 23536787, 2013). "Loss of heterozygosity of the BRCA1 gene was found in 50%–70% of sporadic ovarian carcinomas and loss of heterozygosity of BRCA2 was found in 30%–50%." (PMID 23644885, 2013). "Here, we show for the first time, that the familial breast/ovarian cancer susceptibility gene BRCA1 activates the Notch pathway in breast cells by transcriptional upregulation of Notch ligands and receptors in both normal and cancer cells." (PMID 23863842, 2013). "Breast cancer susceptibility gene 1 (BRCA1) was firstly identified as one of the genes that conferred genetic predisposition to early-onset breast and ovarian cancer." (PMID 23326344, 2013). "The present study sought to correlate whole-exome mutation burden in tumor tissue (Nmut) to treatment outcome in ovarian cancer patients, and to examine this relationship in patients with BRCA1 and BRCA2 mutations in their ovarian tumors." (PMID 24265793, 2013). "Real-time PCR and immunohistochemical analysis showed that the levels of AGTR1 mRNA and protein were increased in non-BRCA1-mutated ovarian cancer compared to adjacent normal tissue (P < 0.05)." (PMID 24321324, 2013). "In this first study of the prevalence of CHEK2 germ line mutations in 145 BRCA1/2-negative early-onset and familial breast and/or ovarian cancer from Pakistan two potentially deleterious mutations were identified." (PMID 23806170, 2013). "Two BRCA1 mutations found in high risk breast/ovarian cancer families in Thailand are missense mutation in exon 11 in which the bases change from T to C at nucleotide 2685 and nonsense mutation of deleted A at nucleotide 3300." (PMID 23393598, 2013).